KIR2DL3 (killer cell immunoglobulin like receptor, two Ig domains and long cytoplasmic tail 3)
Description:
Receptor on natural killer (NK) cells for HLA-C alleles (HLA-Cw1, HLA-Cw3 and HLA-Cw7). Inhibits the activity of NK cells thus preventing cell lysis.
Synonyms: NKAT-2; CD158b2; KIRCL23; NKAT2; cl-6; nkat2a; nkat2b; p58; CD158b; GL183; KIR-023GB; KIR-K7b; KIR-K7c; KIR2DL; NKAT
Tractability: Antibody: a drug acting on it is in phase 2 or 3 trials; its Gene Ontology location is reachable by antibodies, with high confidence; UniProt places it where antibodies can reach, with medium confidence; UniProt predicts a signal peptide or a membrane-spanning region.
Target class: Membrane receptor
Gene: Protein-coding gene on chromosome 19 (54,738,513 to 54,753,061, forward strand). Ensembl gene ENSG00000243772.
Subcellular location: Cell membrane
Pathways (Reactome):
Immune System: Immunoregulatory interactions between a Lymphoid and a non-Lymphoid cell
Gene Ontology:
Molecular function: identical protein binding; protein binding; antigen binding; immune receptor activity; signaling receptor activity; transmembrane signaling receptor activity
Biological process: immune response; immune response-inhibiting cell surface receptor signaling pathway
Cellular component: membrane; plasma membrane
Genetic constraint (gnomAD): Loss-of-function variants: 39 observed, 24.76 expected, observed/expected ratio (o/e) 1.58, 90% interval 1.21 to 1.92. The synonymous counts are far from expectation, so gnomAD's model fits this gene poorly and the ratio says little. Missense variants: 462 observed, 323.85 expected, observed/expected ratio (o/e) 1.43, 90% interval 1.32 to 1.54. Synonymous variants: 174 observed, 120.29 expected, observed/expected ratio (o/e) 1.45, 90% interval 1.28 to 1.64.
Homologues: Orthologues: chimpanzee KIR2DL6 (84% identical), mouse Kir3dl1 (32% identical), rat Kir3dl1 (32% identical), mouse Kir3dl2 (31% identical), tropical clawed frog xilr1 (16% identical). Paralogues in human: KIR2DL1 (91% identical), KIR3DL2 (85% identical), KIR3DL1 (84% identical), KIR3DL3 (74% identical), KIR2DL4 (46% identical), KIR2DS4 (45% identical), LILRB1 (37% identical), LILRB2 (36% identical), LILRB3 (35% identical), LILRB5 (33% identical), LILRA4 (29% identical), LILRA6 (29% identical), and 13 more.
Diseases named in the same sentence as KIR2DL3 in open-access papers:
KIR2DL3 is named in the same sentence as 77 diseases in open-access papers, as found by Europe PMC text mining. Sharing a sentence is not in itself a finding about the gene and the disease. The quoted sentences say what the papers report.
COVID-19 (9 papers, 2021 to 2025). A disease caused by infection with severe acute respiratory syndrome coronavirus 2. "In a study examining the immunogenetics of COVID-19, a positive correlation was discovered between KIR2DL3 and daily mortality rates, while an inverse association was observed between activating KIR2DS2 and daily mortality rates." (PMID 40391199, 2025). "Genetic analysis in a Sardinian population revealed a prevalence of inhibitory KIR receptors like KIR2DL1 and KIR2DL3 in COVID-19 patients, indicating increased susceptibility in individuals with such genetic profiles." (PMID 40244151, 2025). "In conclusion, our results confirm previous findings and bring forward additional evidence to suggest that carrying a certain KIR gene content (KIR2DL3,2DS4del and haplotype A) is associated with COVID-19 disease severity." (PMID 38943065, 2024). "The results also suggest the inhibitory gene KIR2DL3 and haplotype A are risk factors for the severity of COVID-19." (PMID 38943065, 2024). "A meta-analysis confirmed that KIR2DL3 is associated with increased COVID-19 risk, while KIR2DP1 may reduce this risk." (PMID 40244151, 2025). "The frequency of KIR2DL3+KIR2DL2-/HLA-C1+ other+ was lower in COVID-19 patients than in healthy individuals." (PMID 38202265, 2024). "At the same time, the frequency of KIR2DL3+KIR2DL2-/HLA-C1+Others+ was lower in COVID-19 patients than in healthy individuals (P=0.004, OR=0.477)." (PMID 35874712, 2022). "The frequency of HLA-C1C1, the homozygous receptor for KIR2DL2 and KIR2DL3, was also higher in COVID-19 patients than in healthy controls (47.08% vs 22.45%, respectively; OR=3.074, P <0.001)." (PMID 35874712, 2022). "COVID-19 patients were still less likely to carry KIR2DL3+KIR2DL2-/HLA-C1+O+ than healthy controls (22.23% vs 34.69%, respectively, OR =0.477, P=0.004), suggesting that this genetic combination is still protective in the absence of KIR2DL2." (PMID 35874712, 2022). "In contrast, the frequency of KIR2DL3+KIR2DL2+/HLA-C1+O+ was similar between COVID-19 patients and controls (6.61% vs 7.14%, respectively; OR =1.086, P=0.859)." (PMID 35874712, 2022). "Similarly, the KIR2DL3/HLA-C1+O+ combination was lower in the COVID-19 patients than in healthy individuals (30.74% vs 41.84%, respectively; OR =0.617, P= 0.048)." (PMID 35874712, 2022). "KIR2DL1, KIR2DL3, KIR3DL1 and KIR3DL2 are inhibitory NK cell receptors and enhanced interactions via these receptors on CD8+ T cells could indicate a more balanced functional regulation of CD8+ T cells in mild COVID-19." (PMID 36591270, 2022).
hepatitis C virus infection (8 papers, 2006 to 2024). A viral infection caused by the hepatitis C virus. "Resolution of human hepatitis C virus infection was associated with homozygosity for KIR2DL3 and its C1 ligand." (PMID 21079681, 2010). "Interactions between HLA-Bw4 and KIR3DS1 gene have been observed in cases of delayed progression to AIDS in HIV patients, while the homozygosity of both HLA-C1 and KIR2DL3 is associated with resolution of hepatitis C virus infection." (PMID 17069649, 2006). "stated that the weaker inhibition conferred by KIR2DL3/HLA-C1 was found to be protective in acute Hepatitis C Virus infection, possibly by facilitating stronger NK cell responses." (PMID 39148728, 2024). "In hepatitis C infection, KIR2DL3 homozygosity and HLA-C1 homozygosity are beneficial in both early eradication of infection and response to standard treatment (type I IFN + ribavirin administration)." (PMID 33066279, 2020). "In the context of hepatitis C virus infections, where HLA-C1/C1 haplotype carriers homozygous for KIR2DL3 have a higher probability of resolution, certain HLA-C alleles are now emerging as particularly beneficial." (PMID 21665273, 2011). "For example, CNV of KIR3DL1/S1 influences HIV control and expression differences of KIR2DL3, interacting with HLA-C, may have a profound effect on resolution of hepatitis C virus infection." (PMID 33632228, 2021). "Homozygosity of KIR2DL3 and HLA-C1 alleles has been reported to lead to lower levels of NK inhibition than other pairs of KIR ligand combinations, suggesting that this underlies the enhanced response to hepatitis C." (PMID 33066279, 2020). "To study the interrelationship of these genes on the outcome of hepatitis C, we compared the frequency of IL28B.rs12979860-CC in individuals with and without the protective KIR2DL3:HLA-C1 homozygous genotype from all 3 cohorts (EU, SR, and chronic)." (PMID 21600205, 2011).
cerebral malaria (7 papers, 2012 to 2019). A sequestration of Plasmodium falciparum in the brain, which can cause coma and/or seizures. "We herein show that presence of both KIR2DL3 and its cognate HLA-C1 ligand in malaria patients was strongly associated with the development of human cerebral malaria." (PMID 22412373, 2012). "Conversely, the KIR2DL3-HLA-C1 interaction was significantly associated with susceptibility to cerebral malaria in a case-control study of patients from Thailand." (PMID 23346087, 2012). "In contrast, no other KIR-HLA pairs showed a significant association with cerebral malaria, suggesting that the NK cell repertoire shaped by the KIR2DL3-HLA-C1 interaction shows certain functional responses that facilitate development of cerebral malaria." (PMID 22412373, 2012). "In contrast, KIR2DL3-HLA-C1 was significantly associated with susceptibility to cerebral malaria in this study." (PMID 22412373, 2012). "A recent observation in keeping with this hypothesis is that the relatively weakly inhibitory combination of KIR2DL3 and C1 is a risk factor for cerebral malaria, and the activating combination of KIR2DS1 and C2 may be a risk factor for non-cerebral severe malaria." (PMID 27517293, 2016). "Taken together, these results suggest that natural selection by cerebral malaria has operated to avoid KIR2DL3-HLA-C1 interaction in malaria high-endemic populations." (PMID 22412373, 2012). "Taken together, the present results show a significant association between the KIR2DL3-HLA-C1 receptor-ligand pair and cerebral malaria, and the signature of natural selection acting on both KIR2DL3 and HLA-C1 due to cerebral malaria." (PMID 22412373, 2012). "Those analyses suggested that the significant association of KIR2DL3-HLA-C1 combination with cerebral malaria observed in this study is not due to population stratification." (PMID 22412373, 2012). "We found that the combination of KIR2DL3 and its cognate HLA-C1 ligand was significantly associated with the development of cerebral malaria when compared with non-cerebral malaria (odds ratio 3.14, 95% confidence interval 1.52–6.48, P = 0.00079, corrected P = 0.02)." (PMID 22412373, 2012). "In our study design, which focused on the analysis of cerebral malaria after infection, the effect of the HLA-C1 and KIR2DL3 combination on susceptibility to infection could not be analyzed." (PMID 22412373, 2012). "Since KIR2DL3 is on the centromeric KIR A haplotype, the presence of both centromeric KIR A haplotype and HLA-C1 was also significantly associated with cerebral malaria when compared with non-cerebral malaria (OR 3.14, 95%CI 1.52–6.48, P = 0.00079)." (PMID 22412373, 2012). "Because the presence or absence of KIR2DL1 is a simple distinction of two centromeric KIR B regions and KIR2DL1 is in positive linkage disequilibrium with KIR2DL3, we also examined whether the presence or absence of KIR2DL1 in combination with HLA-C1 was associated with cerebral malaria." (PMID 22412373, 2012).
viral infection (6 papers, 2011 to 2024). "Similar results have been found in another model of treatment of a persistent viral infection, hepatitis C (HCV): the presence of KIR2DL3 was associated with better response to anti-HCV treatment." (PMID 22073315, 2011). "KIR2DL3's weaker inhibition may result in greater activation of NK cells and, consequently, in more efficient control of viral infection." (PMID 22073315, 2011). "The analysis of KIR2DL3+/C2C2 frequency showed a statistically significant increase comparing male AC patients without viral infection and healthy controls (23.6% vs. 15%; p = 0.026)." (PMID 38397937, 2024). "The analysis of KIR2DL3+/C1+ showed a high frequency comparing healthy controls and male AC patients without virus infection (85% vs. 76.4%; p = 0.026)." (PMID 38397937, 2024). "KIR2DL3, but not KIR2DL2 has been shown to be protective against viral infection such as hepatitis C virus and also against fulminant malaria." (PMID 25359276, 2015). "The presumed mechanism underlying this observation is that the weaker inhibitory interaction of KIR2DL3 with C1, but not the stronger inhibitory interaction of KIR2DL2 and KIR2DL1 with C1 and C2, could allow penetrance of activating signals during viral infection." (PMID 29664957, 2018).
malaria (5 papers, 2012 to 2019). Malaria is a serious and sometimes fatal disease caused by a parasite that commonly infects a certain type of mosquito which feeds on humans. "Further research revealed that the frequency of the combination of the KIR2DL3-HLA-C1 in the malaria high-risk population was maintained at a low level." (PMID 23251287, 2013). "On empirical distribution, the GF*GF index of KIR2DL3 and HLA-C1 also showed significant difference between malaria high-endemic and low-endemic populations (above the 98th percentile)." (PMID 22412373, 2012). "Furthermore, the frequency of the KIR2DL3-HLA-C1 combination was found to be significantly lower in malaria high-endemic populations." (PMID 22412373, 2012). "In addition, comparison of both the KIR2DL3 and HLA-C1 gene frequencies between malaria high-endemic and low-endemic populations suggest that natural selection has acted on both KIR2DL3 and HLA-C1." (PMID 22412373, 2012). "In addition, the gene frequency of the KIR2DL3 and HLA-C1 combination was found to be significantly lower in populations with high-endemic malaria." (PMID 22412373, 2012). "Thus, we tested the hypothesis that the frequency of the KIR2DL3-HLA-C1 combination is lower in malaria high-endemic populations due to natural selection by fatal malaria." (PMID 22412373, 2012). "Although HLA class I is not expressed on erythrocytes, KIR2DL3-expressing NK cells can respond to inflamed tissues during blood-stage malaria." (PMID 22412373, 2012).
melanoma (5 papers, 2021 to 2025). A malignant, usually aggressive tumor composed of atypical, neoplastic melanocytes. "In one study, KIR3DL1 and KIR2DL3 were expressed at higher levels on the NK cells of melanoma patients, while other studies found an increase in KIR2DL1 and KIR2DL2/2DL3." (PMID 33802954, 2021). "In a different study, KIR2DL3 was found to be a protective marker for nodular and ulcerated melanoma." (PMID 33802954, 2021). "Moreover, the KIR2DL3/HLA-C1 combination decreased in patients with melanoma and sentinel lymph node melanoma metastasis." (PMID 40244151, 2025). "Meanwhile, higher expression of KIR2DL3, a receptor that inhibits NK cell activation, has been reported in stage III and IV melanoma patients compared to stage I melanoma, and several clinical trials are underway to test inhibitors, including Lirilumab and ASP98374." (PMID 37047539, 2023). "The first association study observed an increased frequency of KIR2DL2 and KIR2DL3 in combination with the HLA-C ligand and an increased frequency of KIR2DS1 in the absence of the HLA-C ligand in patients with melanoma." (PMID 40244151, 2025).
HCMV infection (4 papers, 2018 to 2024). "In summary, our results suggest that genotyping recipients for the KIR2DS2, KIR2DL2, and KIR2DL3 genes may help predict the occurrence of posttransplant CMV infection." (PMID 30696053, 2019). "Our results showed that subjects who had KIR2DL3 and KIR2DL2–HLA-C1 were more likely to develop CMV infection." (PMID 30696053, 2019). "The multivariate analysis revealed that the lack of KIR2DS2 (p = 0.035), the presence of KIR2DL3 (p = 0.075), and the presence of KIR2DL2–HLA-C1 (p = 0.044) were risk factors for posttransplant CMV infection." (PMID 30696053, 2019).
cervical carcinoma (3 papers, 2015 to 2025). A carcinoma arising from either the exocervical squamous epithelium or the endocervical glandular epithelium. "This latter evidence contrasts with a study on an Italian cohort, which found an association between the KIR2DL2/HLA-C1 and KIR2DL3/HLA-C1 pairs and invasive cervical cancer at high risk." (PMID 40244151, 2025). "Additionally, a significantly higher frequency of KIR2DL3 was observed in women with HPV infection compared to those with cervical carcinoma, suggesting a possible protective effect against tumor development." (PMID 40244151, 2025). "HPV+ cervical cancer cells maintain NK cell inhibition via HLA-C/KIR2DL2 and HLA-C/KIR2DL3 interactions." (PMID 35174079, 2022). "As HPV+ invasive cervical cancer patients display upregulation in HLA-C/KIR2DL2 and HLA-C/KIR2DL3 antigen pairs, enhancing the HLA-C/KIR interaction may suppress normal NK cell function in HPV+ cervical cancer patients." (PMID 35174079, 2022).
chronic hepatitis C (3 papers, 2014 to 2018). "While, we were unable to KIR genotype the present patient cohort, to allow us to precisely examine KIR2DL2 expression, we did observe maintenance of KIR2DL3 expression and down-regulation of KIR2DL1 and KIR3DL1 in chronic hepatitis C compared to healthy controls." (PMID 28533779, 2017).
HIV-1 infection (3 papers, 2013 to 2023). The type species of lentivirus and the etiologic agent of acquired immunodeficiency syndrome (AIDS). "In recent years multiple studies have drawn attention to the potential role of HLA-C and its cognate inhibitory receptors, KIR2DL1, KIR2DL2, and KIR2DL3, in the intrinsic control of HIV-1 infection." (PMID 35911762, 2022). "Assessment of KIR2DL3 and KIR3DL1/DS1 did not reveal any significant differences between subsets of NK cells or the HIV-1 infection status of the subject." (PMID 24351015, 2013).
acute myeloid leukemia (2 papers, 2021 to 2024). Acute myeloid leukemia (AML) is a group of neoplasms arising from precursor cells committed to the myeloid cell-line differentiation. "Phase 1 studies of IPH2101, a human IgG4 mAb against KIR2DL1, KIR2DL-2 and KIR2DL-3, illustrated that blocking KIRs with IPH2101 enhances NK cell cytotoxicity against acute myeloid leukemia (AML) and multiple myeloma (MM) without eliciting autoimmune response." (PMID 35008589, 2021).
ankylosing spondylitis (2 papers, 2020 to 2022). An autoimmune chronic inflammatory disorder characterized by inflammation in the vertebral joints of the spine and sacroiliac joints. "For instance, ankylosing spondylitis is one of these rheumatic diseases in which the frequency of two KIR genes (KIR2DL3 and KIR2DL5) and two HLA ligands (HLA-B27 and HLA-C2Lys80) was significantly different between AS patients and healthy controls." (PMID 33015197, 2020).
autoimmune disease (2 papers, 2020 to 2024). A disorder resulting from loss of function or tissue destruction of an organ or multiple organs, arising from humoral or cellular immune responses of the individual to their own tissue constituents. "Based on our observations, it may be insightful to investigate the prevalence of CD8+ T cell mediated autoimmune diseases in patients with altered expression of NK regulatory receptors, such as KIR2DL3 and KIR2DS3." (PMID 32117809, 2020).
Chagas disease (2 papers, 2015 to 2021). A parasitic infection caused by Trypanosoma cruzi. "In the current study, KIR2DL3 was not significantly different in any of the comparisons, revealing a possible distinction between these receptors in NK-cell regulation in the cardiac form of Chagas disease." (PMID 25978047, 2015).
Crohn disease (2 papers, 2014 to 2023). A gastrointestinal disorder characterized by chronic inflammation involving all layers of the intestinal wall, noncaseating granulomas affecting the intestinal wall and regional lymph nodes, and transmural fibrosis. "As in ulcerative colitis, human data studies show a negative influence of KIR2DL2/KIR2DL3 in Crohn's disease development and a protective effect for the KIR2DL1/HLA-C2 interaction." (PMID 25310588, 2014).
Diabetes (2 papers, 2022 to 2025). "Collectively, these results suggest that KIR3DL1 and KIR2DS4 as well as KIR2DL3 can be associated with diabetes and hypertension, respectively, among people living and aging with HIV." (PMID 35071606, 2022).
endometriosis (2 papers, 2021 to 2023). The growth of functional endometrial tissue in anatomic sites outside the uterine body. "We found that, except for FGB, KIR2DL1, and KIR2DL3, all other hub genes showed significantly different expression levels in the endometriosis and normal control groups." (PMID 37662927, 2023). "Notably, the study uncovers two previously unknown genes, KIR2DL3 and FGB, in endometriosis, contributing to the understanding of potential genetic factors in the disease." (PMID 37662927, 2023).
graft versus host disease (2 papers, 2020 to 2024). An immune system disorder that occurs after allogeneic hematopoietic stem cell transplant and is a reaction of donor immune cells against host tissues. "Cyclophosphamide (Cy) in the graft-versus-host disease (GvHD) prevention protocol downregulated KIR2DL1 to just 25% of the original donor value, and the FEAM (Fludarabine + Etoposid + Ara-C + Melphalan) conditioning protocol reduced KIR2DL3." (PMID 33138211, 2020).